HLA-B (major histocompatibility complex, class I, B)
Diseases named in the same sentence as HLA-B in open-access papers (continued):
Sharing a sentence is not in itself a finding about the gene and the disease.
infection (continued). "Similar results were also observed in the percentage of RBD(BA.5.2)+CD19+CD27+ memory B cells, confirming the reduction of memory B cells in HLA-B*15 individuals after BA.5.2 infection." (PMID 39257586, 2024). "Statistical analysis revealed that HLA-B*15 populations had significantly lower percentages of memory B cells than non-HLA-B*15 cohorts (others) from the vax booster stage to the Omicron BA.5.2 infection stage." (PMID 39257586, 2024). "To directly test this assumption and define the role of OC43-elicited T cells that are cross-reactive with SARS-CoV-2, we develop a model of sequential infections with OC43 followed by SARS-CoV-2 in HLA-B*0702 and HLA-DRB1*0101 Ifnar1−/− transgenic mice." (PMID 38278784, 2024). "These African apes have HLA-B orthologs and are infected by parasites in the same subgenus (Laverania) as P. falciparum, but the consequences of these infections are unclear." (PMID 36823144, 2023). "This is in line with reports by other groups that HLA-B*57 is associated with a better suppression of HIV-1 replication and a more favorable course of HIV-1-infection." (PMID 36851781, 2023). "Overall, one in five individuals (20%) who remained asymptomatic after infection carried HLA-B*15:01, compared with 9% among patients reporting symptoms." (PMID 37468623, 2023). "Supporting the role of HLA-B*15:01 in mediating asymptomatic infection, we found a highly similar frequency distribution of this allele in asymptomatic versus symptomatic patients in two independent cohorts." (PMID 37468623, 2023). "The current study definitively demonstrated that PolTY9 is an HLA-B*15:02-restricted epitope in subtype A/E infection." (PMID 36154612, 2022). "Supporting the role of HLA-B*15:01 in mediating asymptomatic infection, these results replicated in two independent data sets." (PMID 34031661, 2022). "In this context, along with evidence that the HLA-B molecule's affinity to SARS-CoV-2 epitopes plays a role in the infection." (PMID 35669157, 2022). "For example, infection by MERS-CoV belonging to the same coronavirus family elicits more severe symptoms in a person who carried the HLA-B 46:01 genotype." (PMID 36423013, 2022). "A study from 95 South Asian patients showed an increase in the frequency of HLA-B*51 and HLA-DRB1*13 in the fatal group compared to the mild infection group, while increase in the frequency of HLA-B*35 among the mildly infected group." (PMID 35250581, 2022). "HLA-B*57:03 and HLA-B*58:01 are known as protective alleles strongly correlated with lower viral loads in HIV-1 subtype B and C infections." (PMID 35653364, 2022). "While the regulators NLRC5, IRF1, STAT1, and HLA-B were progressively activated through the infection time course in B.6 and B.1.1.8 infections, they were hardly detected in Delta infection." (PMID 36073824, 2022). "In adults the speed and extent of CD8+ T-cell activation following infection, and the nature of the HLA-B-restricted HIV-specific CD8+ T-cell response are together strongly associated with viral setpoint." (PMID 34793581, 2021). "Here, we identified a relationship between HLA-B*27:05 and protection from adenovirus 40/41 infection during the first year of life." (PMID 33910121, 2021). "In this sense, three genetic polymorphisms in the HLA-B gene were related to different SARS-CoV outcomes, including infection predisposition, a protective phenotype, and severe forms of the disease." (PMID 33110916, 2020). "After infection with HCMV, 4/10 tetramerized Fabs restricted to the alleles HLA-A*0101, HLA-A*0201 and HLA-B*0702 showed binding to infected primary fibroblasts." (PMID 32300857, 2020). "We observed that infection with A/Fort Monmouth/1/1947(H1N1) IAV significantly increased the presentation of HLA-B, -C, and -E on lung epithelial cells." (PMID 32321802, 2020).
infection (continued). "Herein this assumption was tested using a large panel of VACV-derived peptides presented by HLA-B*07:02 (B7.2) molecules in a mousepox/ectromelia virus (ECTV)-infection, B7.2 transgenic mouse model." (PMID 32759969, 2020). "Supporting the low TCM infection level as a hallmark of reduced pathogenicity, the TCM from HIV-1 infected Long Term Non Progressors (LTNP) with the protective HLA-B*27 or B*57 alleles are also less infected than transitional-memory CD4-T-cells (TTM)." (PMID 31095640, 2019). "HCMV sero-positivity was shown to dramatically alter the maternal CD8+ T cell repertoire during pregnancy and similar to HIV, T cell responses to HCMV rely heavily on HLA-C-restricted responses because both viruses downregulate HLA-A and HLA-B upon infection." (PMID 31921098, 2019). "HCMV-derived peptides from HLA-B*35:01 and HLA-B*35:08 originate from different proteins and different time points of the infection stage." (PMID 30128813, 2018). "Though HLA-B*15:11 peptides were dominant after infection with LD, only 26% of them were within the IC50 threshold of 500nM." (PMID 30001391, 2018). "Among the selected MHC class I genes, HLA-B was highly up-regulated (40-fold change upon infection with wild-type Cal [NS1_low-PAX_high] virus) and its expression level was lower in Cal [NS1_high-PAX_low] virus compared to other virus-infected conditions." (PMID 30496325, 2018). "First, viral load in natural infection is 4.9–5.2 log10 copies/mL, similar to that in the HLA-B*58:02–positive placebo recipients here (5.1 log10 copies/mL), corresponding to rapid progression and a high risk of further transmissions." (PMID 26951820, 2016). "First, KK10 is by no means the only HIV-specific response, nor is it necessarily the first CD8+ T-cell response to emerge in the very early phase of infection in subjects expressing HLA-B*27." (PMID 26834742, 2015). "In C clade infection, while 72% of HLA-B*35:01-positive individuals carry the escape mutant D260E, Gag-260-D is present in 70% of sequences and is therefore the consensus." (PMID 26834742, 2015). "At recruitment the proportion of patients carrying a HLA-B*57 allele differed between HIV- (12.9%) and HCV-infection (4.2%)." (PMID 26241854, 2015). "The co-carriage of high expression KIR3DL1 genotypes with HLA-B*57 (*h/*y+B*57) is associated with both slow HIV disease progression and protection from infection." (PMID 25330014, 2014). "TNF-α can promote inflammatory response by inducing the production of other proinflammatory cytokines at the vicinity of the infection, and increase the expression of endothelial surface HLA-B by activation of the nuclear transcription factor NF-κB." (PMID 23698783, 2013). "On the contrary, our data suggests that the major effect of HLA-B*57 occurs several weeks to months after infection, arguing for a role of adaptive immunity perhaps mediated by T-cell responses." (PMID 24245727, 2013). "When comparing viral Gag sequences obtained late in infection from HLA-B*57/58:01 progressors and HLA-B*57/58:01 LTNPs, frequent changes in the amino acid sequence were observed for progressors at 5 positions: S126N, L215T, H219Q, M228I, N252H." (PMID 24339913, 2013). "This novel CD8 epitope was located in a highly conserved region of HIV-1 Gag known to contain immunodominant CD8 epitopes, which are restricted by HLA-B*57 and -B*27 in clade B infection." (PMID 21887282, 2011). "A limitation of our study is that only three HLA-B*18:01+ samples were tested, and the previous infection and vaccination histories of these donors are unknown." (PMID 40587260, 2025). "Individuals with HLA-B*15 allele also manifested significantly lower concentrations of the anti-SARS-CoV-2 prototype Nab at M1 post BA.5.2 infection than that from non-HLA-B*15 patients." (PMID 39257586, 2024).
infection (continued). "The effect of HLA-B*57:01 for the control of HIV-1 replication at viral setpoint (meaning in average 18 months after infection by HIV-1) has been demonstrated with numerous cohorts of seropositive subjects, often involving no more than 500 seropositive subjects." (PMID 38146367, 2023). "Furthermore, protective HIV-1-specific T cell responses were predominantly restricted by the HLA-B allele in HIV-1 subtype B and C infections (15, 24, –, 28)." (PMID 36154612, 2022). "A previous study showed that T cell responses to PolTY9 were significantly associated with HLA-B*15:02 in a cohort of individuals infected with subtype B, implying that PolTY9 might be an HLA-B*15:02-restricted epitope in subtype B infection." (PMID 36154612, 2022). "This supports the hypothesis that HLA-B*27:05 reduces the threshold for unfolded protein response activation in infection." (PMID 35254093, 2022). "However, the HLA-B molecules influencing immune control in adults have less impact on paediatric infection." (PMID 34793581, 2021). "MHC variants showed no important associations between class I antigen-presentation genes (HLA-A, HLA-B, and HLA-C) and nonclassical HLA class I genes (HLA-G, HLA-E, and HLA-F) in symptomatic infection susceptibility." (PMID 34650566, 2021). "In Spain, a study conducted in the ICUs of 6 hospitals in the Canary Islands found a trend to a higher infection rate of the alleles HLA-A*32, HLA-B*39 and HLA-C*16, but these p values were not significant after correction for multiple comparisons." (PMID 34344463, 2021). "Next, we determined whether ORFV D1701-VrV, encoding HLA-A*02- and HLA-B*07-restricted DENV epitopes, could activate memory CD8+ T cells from donors who had recovered from a natural infection." (PMID 34944678, 2021). "This led us to speculate that in hosts possessing HLA-B*15:01 allele, previous infection with DENV might worsen the outcome of secondary infection with WNV, SPONV, or ZIKV." (PMID 29692780, 2018). "Thus, post infection the percentages of HLA-A*02:01-bound peptides decreased by 18% while those of HLA-B*15:11 increased by 19%; those of HLA-C*03:03 were unaffected." (PMID 30001391, 2018). "Interestingly, rapid disease progression associated with HLA-B*3503 (Px) begins during primary HIV-1 and remains noticeable during the course of infection." (PMID 28769934, 2017). "Additionally, we compared the CD8+ T-cell responses in the Phambili subjects to those of HLA-B*58:02–positive unvaccinated individuals with natural chronic HIV-1 C-clade infection (n = 66), most of whom (79%) were females recruited in South Africa." (PMID 26951820, 2016). "However, in C clade infection, the majority if HLA-B*35:01-positive individuals can make a response to NY10." (PMID 26834742, 2015). "Interestingly, in both these participants, there was a CTL epitope reversion to consensus by one year post infection despite these individuals possessing the selecting HLA allele as noted for HLA-B*42-HA9 in participant AS2–0016 and HLA-B*58-SW8 for AS2–0341." (PMID 25781986, 2015). "In parallel, the association of HLA-B*07:02 with rapid progression in B clade infection is not observed in C clade infection." (PMID 26834742, 2015). "However, in B clade infection, 96% of HLA-B*35:01-positive individuals carry D260E, Gag-260-D is present in only 12% of sequences, and Gag-260-E is therefore the consensus." (PMID 26834742, 2015). "This suggests that besides HLA-B*35 other stressful conditions such as inflammation, infection or oxidative stress may contribute to elevated ER stress and UPR gene expression." (PMID 26669670, 2015). "The finding suggests a mechanistic link between CD4+ T cell count and the virus replication rate, by indicating that HLA-B*5701 subjects with CD4+ T cell counts >750 cells/mm3 within the first 10–11 weeks of the infection will keep HIV-1 replication under better control during the subsequent years." (PMID 25187947, 2014).
infection (continued). "Yet, the data suggest that neither T cell activation nor an initial infection with fitter viral variants would explain the difference in dS substitution patterns between HRPs or LRPs carrying the HLA-B*5701 allele." (PMID 25187947, 2014). "Among patients with the HLA-B*07 genotype, 13.33% were characterized as having primary infection, whereas 7.14% had a secondary infection, suggesting that this allele might be involved in eliciting cross-serotype protective CD8+ T cell responses." (PMID 23818909, 2013). "This includes HLA-B*35: 01, which is associated with rapid progression in B-clade infection but not in C-clade infection." (PMID 24023819, 2013). "The impact of HLA-B*5701 is thus apparent from the onset of infection and, among other factors, may contribute to a reduced viral reservoir." (PMID 23630526, 2013). "Likewise, another recent paper describing an association of HLA-DRB1 alleles with asymptomatic infection did not genotype for HLA-B." (PMID 34031661, 2022). "Besides, research has also shown that patients possessing HLA-B*15:03 genotype may become immune to the infection." (PMID 34016183, 2021). "Our sampling framework did not allow us to discriminate whether the higher parasite prevalence observed among HLA-C*06:02 and HLA-B*53:01 positive individuals resulted from a higher rate of incident infection or if it instead resulted from delayed clearance of parasites from the blood." (PMID 33815410, 2021). "This may be regarded as “immune-attenuation” and suggests that alongside ART, CD8 T-cells may play an important role in controlling HIV infection and potentially mediate eradication of viral reservoirs of infection through interaction with various HLA types such as HLA-B*27:02." (PMID 34587974, 2021). "Besides, research have also shown that patients possessing HLA-B*15:03 genotype may become immune to the infection." (PMID 34016183, 2021). "The Taiwan indigenous peoples had considerably low reports of the SARS-CoV-1 probably because they have no HLA-B* 4601 but high frequency of HLA-B* 1301 instead which makes them genetically distinct from the Taiwanese general population who were more susceptible to severe cases of the infection." (PMID 38624552, 2020). "Thus, these decidual CD8+ T cells may provide cellular immunity for infected maternal cells that express HLA-A and HLA-B and limit the spread of infection to trophoblasts and/or the fetus." (PMID 31921098, 2019). "Although in this case both children expressed HLA-B*81:01 that is associated with slow progression in adult infection, large cohort studies indicate that ‘protective’ HLA alleles, such as HLA-B*57, HLA-B*58:01 and HLA-B*81:01, do not significantly influence paediatric disease progression." (PMID 27608713, 2016). "CD8 CTL specific for HIV-1, HSV-2, and EBV HLA-B*27 and HLA-B*57 restricted epitopes were resistant to Treg cell-mediated suppression, explaining how such cells continue to proliferate and control infection(s) in LTNP, which might also apply to the virus-specific CD4 T cells." (PMID 23459797, 2013). "Human infection with mycobacteria has been demonstrated in pre-urban Egypt and in pre-Columbian Peru, observations consistent with the hypothesis that mycobacterial infection has driven the diversity and peptide-binding repertoire of the HLA-B locus." (PMID 17892322, 2007). "Similarly, HLA‐B*35:01, which also harbours Serine 116 and showed strong binding to several SARS‐CoV‐2 epitopes, has been implicated in HIV infection, where amino acid changes at position 116 were associated with differences in peptide binding stability and infection outcomes." (PMID 41314220, 2025). "Likewise, we have previously shown that vaccination of HLA-A*2402 and HLA-B*0702 transgenic mice with the DENV1-NS polyepitope, which expresses five and eight epitopes restricted by these alleles, respectively, induced a significant protection against DENV1 infection." (PMID 39418312, 2024).
infection (continued). "In NAc homogenates, enrichment analyses identified pathways related to immune modulatory pathways, including various types of infection (e.g., KRT14,16,17; HLA-B) and leukocyte migration (e.g., JAM2; PLCG1)." (PMID 37674018, 2023). "Binding between Bw4 on HLA-B expressed by a healthy cell and KIR3DL1, an inhibitory receptor, prevents the NK cell-mediated destruction that can occur when infection results in the downregulation of HLA-B50." (PMID 36823144, 2023). "A total of 1735 HBeAg-seronegative CHB patients with genotype B or C infection of the community-based REVEAL-HBV cohort were genotyped for rs1710 (HLA-G) and rs2770 (HLA-B) using TaqMan assay." (PMID 36611047, 2023). "In the current study, we identified 6 novel HLA-B*15:02-restricted epitopes (NefFL9, GagHL9, GagNM10, PolTF9/LF10, and PolTY9) in HIV-1 subtype A/E infection." (PMID 36154612, 2022). "Studies containing patients diagnosed using the 1997 WHO guidelines and possessing HLA-A*24 or HLA-B*44 that were diagnosed with DHF or DF, including primary or secondary infection, and studies measuring odds ratios (ORs) were included." (PMID 36532922, 2022). "Finally, the HLA-B*5701 variant, which is currently extensively used in clinical practice because of the associated abacavir hypersensitivity, is widely associated with a significant protective effect by inhibiting HIV replication and delaying infection progression." (PMID 35407496, 2022). "However, the HLA-B molecules that in adults confer strong protection against progression, or that are associated with more rapid disease progression, did not significantly contribute to outcome in paediatric infection." (PMID 34793581, 2021). "For the HLA-A*33:03 restricted M1124–134 and HLA-B*44:03 restricted NP319–330, presentations were detected at 0.5 h after infection (beginning after the first-hour infection), however, at that time the presentation of M158–66 was barely detectable." (PMID 34198851, 2021). "As a group, the HLA-B*57:01-positive patients showed initially higher CD4 T-cell counts, which were similar after 3 years of infection." (PMID 32350076, 2020). "After infection with CMV, MRC-5 cells down-regulated their surface expression of HLA-B, as measured by an antibody targeting the Bw4 epitope of HLA-B." (PMID 31723004, 2019). "Based on those findings, we expect that, under TAP-inhibited conditions, empty forms of all RIT HLA-B can synergize with reduced levels of antigenic peptide-bound versions to facilitate and maintain some level of CD8+ T cell surveillance of infections." (PMID 29995954, 2018). "We expected that under infection conditions which inhibit TAP function, cells expressing RIT HLA-B would be more resistant to NK cell lysis." (PMID 29995954, 2018). "The 1.3 log10 lower viral set point in HLA-B*58:02–positive vaccinees and the inability of >50% to meet the CD4+ T-cell count criteria for ART initiation by 600 days after infection are consistent with vaccine-mediated protection against rapid progression." (PMID 26951820, 2016). "Maximum fold changes of 11.9, 10.9 and 5 were observed for the transcription of HLA-B in ECV, HBMEC and HFF respectively at 30 h after infection." (PMID 24236107, 2013). "Therefore, we speculate that Mtb antigens may preferentially bind to HLA-B molecules, that Mtb preferentially interferes with HLA-A processing and presentation, that infection with Mtb leads to selective upregulation of HLA-B, or that HLA-B is preferentially delivered to the Mtb phagosome." (PMID 17892322, 2007). "Both cohorts from China (Beijing and Fudan groups) showed no significant bias toward symptomatic or asymptomatic infection among HLA-B*15:01+ individuals, resulting in insignificant odds ratios." (PMID 40892914, 2025). "We therefore sought to identify HIV-1-specific HLA-B*15:02-restricted epitopes and then investigated whether T cells specific for these epitopes suppressed HIV-1 replication in subtype A/E infection." (PMID 36154612, 2022).